ANKRD35 (ankyrin repeat domain 35)
Synonyms: FLJ25124
Tractability: Antibody: the Human Protein Atlas places it where antibodies can reach. PROTAC: ubiquitination databases record sites on it.
Gene: Protein-coding gene on chromosome 1 (145,866,560 to 145,886,088, reverse strand). Ensembl gene ENSG00000198483.
Subcellular location (Human Protein Atlas): Plasma membrane; Basal body; Nucleoplasm; Primary cilium; Primary cilium transition zone; Vesicles
Gene Ontology:
Molecular function: actin binding
Genetic constraint (gnomAD): Loss-of-function variants: 102 observed, 112.31 expected, observed/expected ratio (o/e) 0.91, 90% interval 0.77 to 1.07. The upper end of that interval is the gene's LOEUF score, 1.07, which puts it in group 4 of 6, group 1 being the genes least tolerant of losing a copy. Missense variants: 1,240 observed, 1,267.4 expected, observed/expected ratio (o/e) 0.98, 90% interval 0.93 to 1.02. Synonymous variants: 515 observed, 528.14 expected, observed/expected ratio (o/e) 0.98, 90% interval 0.91 to 1.05.
Homologues: Orthologues: chimpanzee ANKRD35 (98% identical), pig ANKRD35 (84% identical), rabbit ANKRD35 (83% identical), mouse Ankrd35 (82% identical), dog ANKRD35 (82% identical), guinea pig ANKRD35 (81% identical), rat Ankrd35 (80% identical), tropical clawed frog ankrd35 (30% identical), Caenorhabditis elegans dhhc-13 (7% identical), Caenorhabditis elegans dhhc-14 (7% identical). Paralogues in human: ZDHHC13 (10% identical), ZDHHC17 (10% identical).
Diseases named in the same sentence as ANKRD35 in open-access papers:
ANKRD35 is named in the same sentence as 4 diseases in open-access papers, as found by Europe PMC text mining. Sharing a sentence is not in itself a finding about the gene and the disease. The quoted sentences say what the papers report.
cervical cancer (1 paper, 2022). A primary or metastatic malignant neoplasm involving the cervix. "In the present study, the immune subtype-relevant signature (covering TMEM125, TFF1, DECR2, LONRF3, DAPL1, and ANKRD35) was quantified, which predicted cervical cancer recurrence accurately and independently." (PMID 36313466, 2022).
leprosy (1 paper, 2017). Leprosy is a chronic infectious disease affecting primarily the skin and peripheral nervous system. "We found that five gene variants including gene GAL3ST4, CHGB48, CHGB23, GLT8D2 and ANKRD35 were more frequently reported than the other ten variants among the remaining six patients from two leprosy families by means of gene sequencing (data not shown)." (PMID 29180661, 2017).
cancer (1 paper, 2016). A tumor composed of atypical neoplastic, often pleomorphic cells that invade other tissues. "These variants were found in genes associated with cancers (ANKRD35, DNAH9, MAGEC1, TOX3) or participating in cancer-related signaling pathways (THSD1, MORN2, PTCRA)." (PMID 26822197, 2016).
tumor (1 paper, 2023). "Higher expression of CXCL13 and HEYL in tumor cell than normal cell was found, as well as the lower expression of ANKRD35 and PDCD1LG2." (PMID 37397391, 2023).